BRAF (B-Raf proto-oncogene, serine/threonine kinase)
Diseases named in the same sentence as BRAF in open-access papers (continued):
Sharing a sentence is not in itself a finding about the gene and the disease.
melanoma (continued). "Furthermore, the effectiveness of MEK inhibitors is not restricted to BRAF mutant melanomas but also extends its efficacy in treating uveal melanoma, characterized by mutations in the GNAQ or GNA11 gene." (PMID 38534742, 2024). "Microscopy images of GFP-positive melanoma cells and MTT assays following treatment in the context of CSF conditioned by melanoma/meningeal cells co-culture (C-CSF) both show profound survival-promoting effects and lack of BRAF inhibitor sensitivity with conditioned CSF." (PMID 38866016, 2024). "LGK974 is under clinical investigation in melanoma, pancreatic cancer, triple-negative breast cancer, cervical squamous cell cancer, esophageal squamous cell cancer, lung squamous cell cancer (NCT01351103) and BRAF mutant colorectal cancer (NCT01351103 and NCT02278133)." (PMID 39684513, 2024). "Continuous exposure to MAPK-targeted therapies, such as BRAF and MEK inhibitors (BRAFis and MEKis), can trigger metabolic reprogramming to promote cell state transitions, known as phenotype plasticity, enabling melanoma cells to persist, ultimately contributing to disease relapse." (PMID 37616051, 2023). "This difference may be attributed to feedback activation of HER3 transcription by RAF or MEK inhibitors in BRAF-mutant thyroid cancers, but not in BRAF-mutant melanomas." (PMID 37479689, 2023). "Importantly, persistently elevated AR expression in melanoma cells did not block but rather subverted the transcriptional response of melanoma cells to BRAF inhibition." (PMID 37838724, 2023). "In melanoma, resistance mechanisms emerging after treatment with BRAF-targeted therapy are well known and they correspond mainly to recovery of MEK/ERK signaling or activation of PI3K/AKT signaling, through BRAF amplification and alternative splicing or alterations in RAS, MEK, and ERK10." (PMID 37231247, 2023). "Furthermore, there is no effective targeted therapy currently available for BRAF wild-type melanoma, accounting for approximately 50% of cutaneous melanoma." (PMID 37508519, 2023). "For the 45 patients with resected melanoma brain metastases undergoing targeted DNA sequencing, molecular classification recapitulated The Cancer Genome Atlas groups (NRAS variant, BRAF variant, NF1 variant, and triple wildtype) with no subtype enrichment within the brain metastasis cohort." (PMID 37589977, 2023). "Notably, in melanoma 25, the upregulation of LINC00589 has been demonstrated to restore sensitivity to the BRAF inhibitor PLX4720 in resistant cells, offering a potential therapeutic avenue for patients resistant to BRAF inhibitors." (PMID 37781073, 2023). "S63845 when used in combination with ABT-199 was more potent in melanoma cells without BRAF mutation whereas combined with encorafenib, a BRAFV600 inhibitor, induced apoptosis in significantly higher percentages of drug-naïve BRAFV600 melanoma cells than either drug alone." (PMID 37835493, 2023). "In addition, class 3 BRAF mutations were more prevalent in HRAS-mutant salivary gland (5%), and bladder (9%), and melanoma (11%) cancers, whereas none were present in the respective KRAS- and NRAS-mutant tumors (p<0.05 for all)." (PMID 37503077, 2023). "Specifically, M1 cells exhibit a neural crest–like phenotype and cluster with BRAF-mutant human melanomas, M4 cells have a transitory phenotype and cluster with RAS-mutant human melanomas, and M3 cells have a melanocytic phenotype and cluster with human triple-WT (BRAF/RAS/NF1-WT)." (PMID 37471141, 2023). "Since the introduction of v-raf murine sarcoma viral oncogene homolog B1 (BRAF) and methyl ethyl ketone protein kinase (MEK) inhibitors, followed by immunotherapy with immune checkpoint inhibitors (ICIs), the overall survival of patients with stage III and IV melanoma has greatly improved." (PMID 37176042, 2023).
melanoma (continued). "BRAF inhibitors have produced an impressive response rate in BRAFV600E melanoma, but not in CRC3." (PMID 36759733, 2023). "Moreover, BRAF inhibition (BRAFi)-resistant melanoma cells were shown to present with deregulation of the fatty acid synthase (FASN), which was proposed as a metabolic target for melanoma, prostate, and breast cancer treatment." (PMID 37495601, 2023). "Considering the BRAF heterogeneity of melanoma, a single biopsy may not be sufficient to uncover the entire BRAF status of a patient, and multiple samples from different sites may be preferable." (PMID 36737739, 2023). "Furthermore, there is no effective targeted therapy currently available for BRAF wild-type melanomas (approximately 50% of cutaneous melanoma)." (PMID 37508519, 2023). "For example, in cells with wild type BRAF, BRAFi binding to one BRAF protomer in a BRAF:BRAF or BRAF:CRAF dimer results in allosteric activation of the non-drug-bound dimer partner resulting in paradoxical activation of ERK1/2 signalling and adventitious tumour growth in non-melanoma tissue." (PMID 37018014, 2023). "Our previous studies indicated that CD271 expression within primary melanomas correlates with a more aggressive tumor phenotype and reduced patient survival, with other studies suggesting that CD271 expression is induced during acquired resistance to BRAF inhibition." (PMID 37189846, 2023). "Interestingly, the enforced expression of these miRNAs is not able to affect the proliferation of BRAF-wt melanoma cells either in the absence or in the presence of NRAS mutations, thus suggesting their specificity only for BRAF-mutated melanomas." (PMID 36418472, 2023). "Mostly based on the experience of melanoma treatment and the recent clinical trials in adult and pediatric (NCT02684058) settings, targeted therapies will rely both on the exact nature of the activating BRAF alteration and on the possible additional alterations." (PMID 36831610, 2023). "Companion diagnoses, such as MSI, ERBB2 staining, EGFR, BRAF, ALK fusion, and BRCA1/2, can be done before the standard treatment, which is another reason why the CGP test is not needed, as the drivers of lung cancer, colon cancer, and melanoma are already known to a certain extent." (PMID 36251535, 2023). "However, the prognosis of melanoma patients with BRAF wild-type has not been significantly improved, as they do not benefit from the BRAF and MEK inhibitor therapy." (PMID 37205993, 2023). "Finally, we show how our PM tool can be used to generate novel hypotheses by comparing melanoma patients that progressed after a first line of ICI and who were treated with either a targeted treatment (BRAF inhibitors) or with an ICI rechallenge." (PMID 37025593, 2023). "BRAF and MEK inhibitors do not appear to be a promising therapeutic regimen for the treatment of melanoma patients with NRAS-mutated metastatic melanoma when applied at the currently used doses for the treatment of BRAFV600E/K melanoma." (PMID 38067230, 2023). "Three BRAF inhibitors, vemurafenib, dabrafenib, and encorafenib have been approved for the treatment of non-resectable BRAF V600E or V600K mutant melanoma and anaplastic thyroid cancer." (PMID 38239196, 2023). "However, two similar reports have indicated that BRAF but not CRAF plays a critical role in initiating NRAS-driven melanoma, even though both display compensatory functions in tumor progression." (PMID 38111008, 2023). "Interestingly, contrary to melanoma, patients with BRAF V600E in their tumors seem to not respond to BRAF inhibitors." (PMID 38201408, 2023).
melanoma (continued). "The previous argument suggested that the exclusive use of ERK2, as opposed to ERK1, in drug-addicted melanoma cells might result from preferential genetic (or physical) interactions of BRAF complex proteins with ERK2 rather than ERK1." (PMID 38023990, 2023). "Thus, we tested the clinically used BRAF inhibitor vemurafenib in A2058 metastatic melanoma cells in comparison to the non-metastatic melanoma cell line A375." (PMID 37237519, 2023). "The growth of a BRAF or NRAS mutant nevus is limited by cell-cycle arrest and cellular senescence, which may be interrupted by genetic and genomic disruption of tumor suppressor genes to allow the progression of the lesion to melanoma." (PMID 36834954, 2023). "However, despite the fact that BRAF is very important in the development and progression of melanoma, studies have shown that it alone is not sufficient for tumor genesis." (PMID 35056382, 2022). "To assess the on-target efficacy of vemurafenib to inhibit BRAFV600E activity in zebrafish melanoma, we performed immunofluorescence staining of melanoma sections to assess the MAPK pathway activity using phospho-Erk1/2, a downstream target of activated BRAF signalling." (PMID 35394030, 2022). "Common examples of targeted therapies are the use of BRAF V600E inhibitors in melanoma patients, imatinib to target BCR‐ABL translocations in chronic myeloid leukaemia and PD1/PD‐L1 inhibitors for the immunotherapeutic treatment of melanoma, lung, renal and other cancer types." (PMID 35811332, 2022). "These subtypes are represented by BRAF mutant melanomas, which account for approximately 50% of melanomas; NRAS-, KRAS-, and HRAS-mutant melanomas, which are about 25%; NF1-mutant melanomas (15% of melanomas); and triple-wild-type melanomas, which account for the remaining 10% of cases." (PMID 35563772, 2022). "Shedding of several RTKs, especially AXL, has been shown in patients with breast cancer and melanoma, and their circulating levels exhibited variable reduction in patients with melanoma after treatment with a combination of the MEK inhibitor trametinib and the BRAF inhibitor dabrafenib." (PMID 36358725, 2022). "However, unlike in patients with melanoma, targeted treatments with BRAF/MEK inhibitors are still the subject of current research." (PMID 35198980, 2022). "In contrast to BRAF and NRAS, KIT mutations do not associate with histological subtypes or tumour stage; they do, however, have a close association with increasing age, acral mucosal subtypes of melanoma, and chronic sun-induced damaged sites." (PMID 36232957, 2022). "In addition, BRAFi and MEKi lack efficacy in non-canonical BRAF-mutant and BRAF wild-type CM and in rare melanomas, further curtailing their utility." (PMID 35513054, 2022). "Intriguingly, HER3 phosphorylation has been repeatedly observed as a bypass mechanism of resistance to BRAF and MEK1/2 inhibitors in melanoma, indicating that there may be additional mechanisms in which HER3 plays a critical and central role in acquired resistance." (PMID 35249128, 2022). "Another finding was that inhibiting AURKA impaired melanoma growth and survival regardless of whether the melanoma cells are resistant to BRAF/MEK inhibitors." (PMID 35692844, 2022). "About 80% of benign nevi carry BRAF but none in familial melanomas." (PMID 36613640, 2022). "Notably, the patient with a BRAF V600E mutant ovarian serous carcinoma tumor (i.e., not melanoma) was successfully treated with BRAF inhibitor dabrafenib and MEK inhibitor trametinib (PR ongoing at 10.7+ months)." (PMID 35347205, 2022). "However, it is also reported that CRAF ablation does not affect tumor progression in NRASmut melanoma due to a rapid switch to BRAF-driven activation." (PMID 36551302, 2022).
melanoma (continued). "To further verify the therapeutic effect of lj‐2‐66 on BRAF‐mutant melanoma in vivo, we used a nude mouse xenograft model as described in the methods section and found that lj‐2‐66 suppressed the growth of BRAF‐mutant melanoma in vivo and did not affect the body weight of the mice." (PMID 35332658, 2022). "We previously showed, in a model of BRAF mutant thyroid cancer, that HSV/BRAFi was an effective combination, further improved by the addition of ICI as triple therapy, and here we have further developed this approach in the more common clinical context of melanoma." (PMID 35338089, 2022). "Although lack of USP28 expression in melanoma cells has no impact on cell proliferation, it favors both the development of resistance to BRAF/MEK inhibitor combination therapies in vitro and in vivo and the generation of emergent tumor cells in mouse xenograft experiments." (PMID 35884430, 2022). "Downstream of MEK, increased ERK1/2 kinase activity leads to acquired drug resistance; however, ERK1/2 inhibitors (ERK1/2i) have shown limited clinical activity as single agents in melanoma, including in a patient with non-E/K V600 BRAF mutant CM, and in other solid tumors." (PMID 35513054, 2022). "In melanoma, however, this association is only significant for BRAFV600E mutant tumors, suggesting a role of SLC35B2 particularly in the context of MAPKi treatment which represents a standard treatment in advanced BRAFV600 mutant, but not BRAF wildtype melanoma." (PMID 35798875, 2022). "MEK inhibitors for NF1-mutation melanoma: Although NF1-mutant melanoma patients do not usually express NRAS or BRAF mutations, inhibition of the BRAF, MEK and mTOR pathways may be therapeutic since the NF1 mutation increases RAS/MAPK pathway signalling." (PMID 36232957, 2022). "Additionally, the MEK inhibitor PD0325901 has been shown to be beneficial in melanoma cell line regardless of BRAF status." (PMID 35884733, 2022). "Unfortunately, beyond BRAF, KIT mutations and tumor mutation burden, no clinically validated predictive markers exist in melanoma, although several promising biomarkers have been described, such as the expression of immune-related genes or mutations in the IFN-signaling pathway." (PMID 35628196, 2022). "These chromosomal regions contain genes [GNAQ (9q21.2), BRAF (7q34), PTEN (10q23.31), CCND1 (11q13.3), RREB1 (6p24.3), MYB (6q23.3), and CDKN2A (9p21.3)] involved in the MAPK pathway, which is consistent with the involvement of this pathway in the pathogenesis of melanoma." (PMID 36614156, 2022). "Besides, the combination treatment with v-raf murine sarcoma viral oncogene homolog B1 (BRAF) inhibitors and MEK inhibitors promotes GSDME cleavage and HMGB1 release in melanoma cells, which activate dendritic cells and ultimately lead to the proliferation of T cells to exert its anti-tumor effects." (PMID 35462927, 2022). "Interestingly, high SLC35B2 expression in melanoma was significantly associated with shorter PFI in BRAFV600E mutant, but not BRAF wildtype metastatic melanoma." (PMID 35798875, 2022). "Studies have demonstrated that in the metastatic melanoma cells the expression of tyrosinase is increased and down-regulation of the Tyr gene can affect inhibition of cell proliferation, promote apoptosis, and reduce hyperpigmentation by affecting signaling pathways such as the RAS/BRAF/MAPK." (PMID 35656077, 2022). "Importantly, MMDR is described in three different BRAF mutant melanoma cells, regardless of their transcriptional phenotypic MITF/AXL signature." (PMID 34957688, 2022). "Recent research found that the inhibitor of B-Raf (a member of Raf family of serine/threonine protein kinases) exhibited increased tumor immune infiltration, and the combination of ICB and B-Raf inhibitor showed improved antitumor activity in BRAF V600E-mutant melanoma." (PMID 36713514, 2022).
melanoma (continued). "Interestingly, concurrent expression of CD271 and TNFR2 is not as common among BRAF-mutant melanomas in vivo, which suggests that CD271 expression can also be modulated by the TME." (PMID 35879777, 2022). "We show that Activin-A secretion by melanoma cells inhibits adaptive antitumor immunity irrespective of BRAF status by inhibiting CD8+ T cell infiltration indirectly and even independently of CD4 T cells, at least in part by attenuating the production of CXCL9/10 by myeloid cells." (PMID 35580932, 2022). "In melanoma cells treated with proinflammatory cytokines, the HECT domain-containing E3 ligase ITCH catalyzes the non-degradative K27-linked ubiquitination of BRAF, which leads to PP2A recruitment, 14-3-3 dissociation, and sustained BRAF/MEK/ERK pathway activation." (PMID 36585710, 2022). "The results from the VE-BASKET study which is an open-label, non-randomized, multicohort study for BRAF V600E-mutant non melanoma tumors, showed that in seven PXA treated with vemurafenib only one showed complete response, two showed partial responses, and three patients had stable disease." (PMID 36077798, 2022). "We conclude that intravenous high-dose ascorbate will be beneficial for melanoma patients by interfering with the tumor’s energy metabolism and can be safely combined with standard melanoma therapies such as BRAF inhibitors without pharmacological interference." (PMID 35406796, 2022). "Furthermore, the direct interaction of melanoma cells via β1integrin with the ECM deposited by MAFs, induced intracellular FAK signaling that consequently re-activated the ERK signaling pathway in melanoma cells, following BRAF inhibitor treatment." (PMID 36119516, 2022). "MAFs and dedifferentiated mesenchymal-like melanoma cells can produce and remodel the ECM in response to cues from the TME such as secreted factors (e.g., TGFβ, PDGF, fibroblast growth factor 2), hypoxia, ECM mechanical signals and in response to BRAF inhibitor treatment." (PMID 36119516, 2022). "In addition, the detection of typical genetic alterations in tumors (such as BRAF V600E in melanomas) does not preclude a different diagnosis, as markers are not 100% specific for a certain entity." (PMID 35198980, 2022). "YAP activation induced analogous changes in BRAF melanoma, but not colorectal cells." (PMID 36476495, 2022). "Indeed, BRAF inhibitors enhance β-catenin nuclear accumulation through the induction of BRAF-CRAF heterodimerization and subsequent activation of ERK signaling in both CAFs and melanoma cells, leading to proliferation of melanoma cells." (PMID 35409404, 2022). "However, target therapies are only approved in the case of exon 15/codon 600 BRAF-mutant melanoma, using a BRAF inhibitor with or without MEK inhibitors." (PMID 35628196, 2022). "Interestingly, inhibition of DOT1L prior to the addition of a BRAF inhibitor, but not co-administration of both drugs, enhanced resistance of melanoma cells to the latter drugs." (PMID 35495127, 2022). "In a phase II trial in patients with BRAF V600-mutant melanoma who had previously progressed on BRAF inhibitors (with or without MEK inhibitors) and were off-treatment for at least 12 weeks, dabrafenib plus trametinib rechallenge resulted in antitumor activity." (PMID 36058945, 2022). "Interestingly, we demonstrated that in the absence of BRAF and CRAF, ARAF alone can sustain both ERK activation and proliferation in NRAS-mutated melanoma cells." (PMID 35091687, 2022). "Since melanoma cells with acquired resistance to vemurafenib retained their sensitivity for DCA, these results support DCA as a potentially effective drug regardless of mutational status or sensitivity to BRAF inhibition." (PMID 35409102, 2022). "However, oncogenic BRAF seems not to be sufficient to generate specific metabolic signatures that allow metastatic and non-metastatic melanomas to be differentiated." (PMID 35912100, 2022).